DARS2 (aspartyl-tRNA synthetase 2, mitochondrial)
Diseases named in the same sentence as DARS2 in open-access papers (continued):
Sharing a sentence is not in itself a finding about the gene and the disease.
DARS2 also shares sentences with these, for which no sentence is quoted: neurological disorder (3 papers); cerebellar ataxia (2); adenocarcinoma (1); Alzheimer disease (1); biotinidase deficiency (1); bladder tumor (1); cardiac hypertrophy (1); co-infection (1); dementia (1); epilepsy (1); fragile X tremor/ataxia syndrome (1); glioblastoma (1); Hartnup disease (1); Histiocytosis (1); insomnia (1); Leigh syndrome (1); lung carcinoma (1); Lymphadenopathy (1); maple syrup urine disease (1); metabolic disorders (1); multiple myeloma (1); neurodegenerative disease (1); neuropathy (1); ovarian failure (1); peripheral neuropathy (1); pontocerebellar hypoplasia type 6 (1); sensorineural hearing loss with (1); spastic ataxia (1); tuberculosis (1); type 2 diabetes (1).
A further 2 diseases each share a sentence with DARS2 in 1 paper.